INS (insulin)
Diseases named in the same sentence as INS in open-access papers (continued):
Sharing a sentence is not in itself a finding about the gene and the disease.
Hypoglycemia (continued). "Combined these findings point toward endogenous insulin playing a key role in preventing hypoglycaemia; perhaps directly by stopping secretion when blood glucose levels fall or indirectly through counter‐regulatory hormones such as glucagon." (PMID 30955221, 2019). "Severe hypoglycemia was also significantly reduced from baseline in patients with T1D after they switched the basal insulin to degludec." (PMID 31397845, 2019). "This study indicates that the babies whose mother had gained more weight or used insulin during the perinatal period have a higher possibility of long and repeated neonatal hypoglycemia." (PMID 31023291, 2019). "Factors influencing the amount of carbohydrate intake required to prevent exercise-mediated hypoglycemia include body mass, circulating insulin levels and the type, intensity and duration of exercise." (PMID 31258513, 2019). "Such the fine-tuning mechanism in maintaining blood glucose homeostasis is also found in the islets to prevent a potential hypoglycemia resulting from insulin “overshooting”." (PMID 31404283, 2019). "Patients with the interactions aspirin + insulin, insulin + metformin, and insulin + ramipril were presented with signs/symptoms and abnormal laboratory findings indicating hypoglycemia." (PMID 31607905, 2019). "For these patients it has been proposed that exogenous insulin can be used to lower their blood glucose level and exogenous glucagon can be used to prevent hypoglycemia." (PMID 30893335, 2019). "Glucose, insulin and somatostatin exert inhibitory effects on alpha cell secretion of glucagon, whereas hypoglycemia and amino acids are known to stimulate the secretion of glucagon." (PMID 31443356, 2019). "Among insulin-treated patients the frequency of hypoglycemia is greater in T1D than in T2D patients, and depends on intensive insulin treatment, on regimens of insulin administration, and on age." (PMID 31349701, 2019). "After surgery, this synergy results in hyperinsulin secretion that is inappropriate for the ingested glucose load, and in lean gastrectomy patients with normal insulin sensitivity, the excessive insulin response can be sufficient to drive hypoglycemia." (PMID 30726726, 2019). "Numerous studies have reported a high incidence of potentially serious adverse events of insulin therapy such as hypoglycaemia and hypokalaemia during DKA management." (PMID 31418117, 2019). "In this regard, insulin-induced hypoglycemia is found to be difficult to detect as compared with spontaneous hypoglycemia." (PMID 31042157, 2019). "Patients who were taking insulin were 4.93 times more likely to have history of hypoglycemia as compared with those who were taking OHA only with (AOR = 4.93, 95% CI: 2.05, 11.86)." (PMID 30700277, 2019). "They found the rate of hypoglycemia in patients received basal/bolus insulin injection was threefold of that of the patients in the combinational group." (PMID 31950036, 2019). "Current guidelines to prevent exercise-induced hypoglycemia suggest insulin dose adaptation and/or ingestion of additional carbohydrates in the context of the exercise bout." (PMID 31835538, 2019). "Since diagnosis, appropriate control of glycaemia in T1D requires insulin administration, which can result in side effects, such as hypoglycemia." (PMID 31156453, 2019). "In the 1-wk hypoglycemia prevention group (n = 4), BG levels after insulin were significantly reduced to 3.2 ± 0.3 mM (day 1), 3.3 ± 0.3 mM (day 2), and 3.0 ± 0.2 mM (day 9)." (PMID 31013147, 2019). "Single i.p. insulin injection to fasted C57BL/6 mice gradually decreased blood glucose levels to the 2.4 ± 0.2 mM minimum (hypoglycemia) at 60 min post-injection, then returned to the fasted baseline level by 240 min 4.02 ± 0.19 mM." (PMID 30996341, 2019). "High GI snacks are also recommended in early recovery (1–2 h post exercise) to replenish glycogen stores and to avoid hypoglycemia in this period of heightened insulin sensitivity." (PMID 31258513, 2019).
Hypoglycemia (continued). "Patients had frequent hypoglycemia in early childhood and blood glucose levels were lower than in the normal population, with higher serum insulin levels for concomitant glucose level." (PMID 31939483, 2019). "Insulin use was interrupted in case of normo - and hypoglycaemia with still persisting ketoacidosis in 34/100 (34%) pt, LOS in ICU was found to be 56.2 ± 32.1 vs 35.5 ± 22.5 h, p<0.05." (PMID 30890150, 2019). "Insulin injection is the next available option to treat resistant diabetes; however, hypoglycemia and weight gain are common discouraging side effects." (PMID 31415655, 2019). "This was mainly driven by the significantly lower rates of hypoglycaemia of insulin glargine U100 than NPH insulin." (PMID 31303866, 2019). "We recorded from the surface of the vagus nerve in anesthetized mice (N = 19) using a Cortec Micro Cuff Sling electrode during acute hypoglycemia induced by insulin injections." (PMID 32232099, 2019). "Blood glucose level check-up and meal time adjustment with insulin were the most prevalent prevention options of hypoglycemia; documented in 218 (89%) and 187 (76.3%) of the patients, respectively." (PMID 31093506, 2019). "An insulinoma is diagnosed by the concomitant presence of hypoglycemia (≤40 mg/dL), inappropriately increased insulin levels (>6 U/L), and β-hydroxybutyrate levels ≤2.7 mmol/L." (PMID 31382663, 2019). "In our study, hypoglycaemia awareness improved at the end of a three month structured training programme which included hypoglycemia and insulin management, safe exercise management and increased target blood glucose levels." (PMID 30701953, 2019). "One of the earliest EMS hypoglycaemia studies appeared at odds with what is now common UK paramedic practice, and recommended all insulin treated patients that experience a SHE are transported to EDs." (PMID 33328832, 2019). "Maternal hypoglycemia was included as an outcome between metformin and insulin by 3 studies which involved 352 GDM patients." (PMID 31781670, 2019). "Hypoglycaemia remains a major concern for people with type 1 diabetes and advanced insulin-treated type 2 diabetes." (PMID 30293112, 2019). "During hypoglycemia periods, the serum insulin level was significantly increased in diazoxide-unresponsive patients (mean insulin level, 29.6 ± 32.7 μIU/ml) compared with the diazoxide-responsive patients (mean insulin level, 11.5 ± 8.6 μIU/ml, P < 0.05)." (PMID 31218401, 2019). "Exercise-induced hypoglycemia occurs secondary to a rapid increase in glucose uptake and insulin sensitivity that persists for up to 48 h following exercise." (PMID 30787908, 2019). "They reported the ingestion of TRE leads to lower glucose and insulin responses prior to exercise, and reduces the prevalence of rebound hypoglycemia compared with the ingestion of glucose." (PMID 31035710, 2019). "On the other hand, the sympathetic innervation is unlikely to affect insulin secretion because it mainly inhibits insulin secretion during hypoglycemia state." (PMID 31717308, 2019). "We report that responses to insulin induced hypoglycemia and 2-DG mediated glucopenia are significantly impaired in the ArcPomc−/− mice." (PMID 30503832, 2019). "During the episodes of hypoglycemia, insulin and C-peptide levels were also measured along with blood glucose; both were found to be elevated whenever hypoglycemia occurred." (PMID 31426870, 2019). "Four percent of the study population had incorrectly ordered medications, and one adverse event of hypoglycemia, due to an incorrect and duplicated insulin order, was identified." (PMID 30815027, 2019). "The gold standard for insulinoma diagnosis is the 72-h fasting test: In this cumbersome test, the patient is hospitalized and undergoes a blood sampling for serum glucose and insulin every 6 h, or whenever symptoms of hypoglycemia occur." (PMID 31382663, 2019). "Insulin is one of the most important HAMs, as insulin overdose due to insufficient HAMs knowledge can lead to hypoglycemia." (PMID 30936779, 2019).
Hypoglycemia (continued). "Intraperitoneal injections of insulin (5 U/kg) were administered to induce hypoglycemia once daily for 3 days in the HAAF treatment groups." (PMID 31013147, 2019). "Insulin induced hypoglycemia has been postulated to elicit an adverse sympathoadrenal response that predisposes to arrhythmia and death." (PMID 31775749, 2019). "Free insulin levels at the end of clamp were similar between the hypoglycemia (968.5 ± 149.1 pmol/L) and euglycemia groups (1025.4 ± 81.4 pmol/L, P = 0.996) but significantly higher (P < 0.001) than those in the sham-saline (31.3 ± 6.3 pmol/L) group." (PMID 30252067, 2019). "Here we show that insulin-induced hypoglycemia selectively activates microglia in the hypothalamic arcuate nucleus and this microglial activation likely attenuates full expression of counterregulatory responses to hypoglycemia." (PMID 30996341, 2019). "A few patients experienced hypoglycemia with glucose levels below 70 mg/dL during the monitoring periods in both KT and LT patients except with the use of glucose-lowering agents including insulin in patients with preexisting DM." (PMID 31886275, 2019). "As a consequence of the counter-regulatory response to hypoglycemia, systemic glucose levels are maintained at the expense of glucose uptake and utilization in insulin-sensitive organs such as muscles, adipose tissue and liver." (PMID 31133864, 2019). "Sitagliptin added to combined metformin and insulin therapy showed greater efficacy and good safety regarding hypoglycemia in patients with newly diagnosed T2DM compared with voglibose." (PMID 31038562, 2019). "The episodes of hypoglycemia were almost always after meals, and rarely during periods of fasting, indicating ivacaftor’s effect on insulin secretion is greatest on insulin release in response to a glucose load." (PMID 31010313, 2019). "When compared with insulin, glyburide appears to have worse neonatal outcomes, including more hypoglycaemia, macrosomia, birth injuries, and respiratory distress syndrome, and no improvement in glycaemic control." (PMID 31119029, 2019). "In the pairwise meta-analysis, we observed that metformin had lower incidence of neonatal hypoglycemia compared with insulin (RR, 0.57; 95% CI, 0.49 to 0.66; P < 0.00001)." (PMID 31781670, 2019). "Continuous aerobic activity performed when insulin levels are high will result in a decrease in blood glucose levels and require a reduction in insulin and/or an increase in carbohydrate supplementation to avoid hypoglycemia." (PMID 31258513, 2019). "During the hypoglycemia episode, the average value of blood glucose was 2.3 mmol/L (range 1.5–3.1 mmol/L) and for insulin level was 14.0 uU/mL (range 2.5–37 uU/mL)." (PMID 31094068, 2019). "A limitation of this study was that the relationship between hypoglycemia and insulin dose changes cannot be determined from the results presented here." (PMID 31335194, 2019). "Of the type II DM cases with insulin, 47.1% experienced some type of hypoglycemia and16.8% had severe hypoglycemic episodes within a 6-month period." (PMID 31652253, 2019). "The timing of hypoglycemia with respect to insulin doses and actual doses were also unavailable, though all patients had orders for insulin therapy." (PMID 31775749, 2019). "Hypoglycemia, symptomatic hypoglycemia, and severe hypoglycemia (SH, a circumstance where the patient is unconscious and requires the assistance of someone else) are frequent in T1D and T2D patients who use insulin or in T2D patients on sulphonylureas." (PMID 31349701, 2019). "Its cumbersome administration method and the high chance of side effects such as hypoglycemia and weight gain have made insulin a problematic and debatable option." (PMID 31720147, 2019). "During the 60 days of clinical trials, in one participant, insulin injection was discontinued after 15 days of intervention to avoid hypoglycemia." (PMID 31636690, 2019).
Hypoglycemia (continued). "Although the inhaled insulin powder Afrezza®, which has been marketed, can significantly reduce the incidence of hypoglycemia and relieve the pain of patients, the sales volume and the market feedback of Afrezza® is unsatisfactory as well." (PMID 31257946, 2019). "GH secretion is suppressed by increased glucose levels and is stimulated by insulin-induced hypoglycemia." (PMID 31939483, 2019). "Reduction in insulin doses to prevent exercise-mediated hypoglycemia is typically required for prolonged (>30 min) moderate intensity exercise, particularly if insulin is above basal levels." (PMID 31258513, 2019). "Hypoglycemia also occurred in a patient who received intensive insulin therapy plus an α-glucosidase inhibitor." (PMID 30815039, 2019). "Previous research also observed that women were more likely to experience hypoglycemia during insulin treatment." (PMID 30668524, 2019). "Of the insulin users of the hypoglycemia group, 2 patients used an insulin mixture and 1 patient was on intensive insulin therapy combined with DPP-4 inhibitor therapy." (PMID 30815039, 2019). "Insulin therapy aims to avoid fluctuations (hypoglycemia and hyperglycemia) in BGLs in order to prevent diabetic complications." (PMID 31443473, 2019). "The pharmacotherapeutic regimen that presented the most adverse events (58.3%) was that of triple pharmacotherapy (linagliptin + oral antidiabetic + insulin), with hypoglycemia being the most reported AE in this group." (PMID 31178735, 2019). "In previous studies, the emphasis has been on how to avoid exercise-induced hypoglycemia by means of pre-exercise bolus insulin dose reductions for both continuous and high-intensity interval exercises." (PMID 31174360, 2019). "We observed that neural signals in the vagus nerve respond significantly to insulin-induced hypoglycemia and correlate with dropping blood glucose levels." (PMID 32232099, 2019). "Other factors include clinical inertia, fear of hypoglycaemia, insulin aversion, the need for self-monitoring of blood glucose and non-adherence to prescribed medications." (PMID 30824788, 2019). "This is the first report on intractable hypoglycemia due to co-secretion of insulin from two kinds of primary tumor cells in a single patient." (PMID 29166433, 2019). "Fear of hypoglycaemia, weight gain and restrictive treatment regimens are key impediments to insulin use." (PMID 31796048, 2019). "The recently proposed bi-hormonal AP system controls both insulin and glucagon pump to reduce hypoglycemia while maintaining intensive insulin treatment, and thus does not require carbohydrate counting by patients." (PMID 31694629, 2019). "Antecedent insulin-induced hypoglycemia reduces plasma epinephrine levels after subsequent hypoglycemia." (PMID 31013147, 2019). "In contrast, we reported a higher proportion of CSII‐treated patients that experienced non‐severe hypoglycemia during Ramadan fasting than those treated with either premixed insulin or MDI regimen." (PMID 30938074, 2019). "The diagnosis of insulinoma therefore requires confirmation of the presence of hypoglycemia with evidence of inappropriate insulin secretion and the identification of a pancreatic mass by medical imaging or angiography." (PMID 32009878, 2019). "A previous study that compared patients on insulin mixture therapy with those on basal-bolus therapy demonstrated significantly high incidence of hypoglycemia in the insulin mixture therapy group." (PMID 30815039, 2019). "In recent studies, bihormonal pump therapy has shown improvement in mean blood glucose and reduction in incidence of hypoglycemia in comparison with insulin only pump therapy." (PMID 30875898, 2019). "Hybrid closed-loop systems have harnessed the data gathered with CGM use to aid in basal insulin dosing and hypoglycemia prevention." (PMID 30875898, 2019).
Hypoglycemia (continued). "In patients treated with insulin, hypoglycemia can happen during, immediately after, or many hours after acute exercise, such as during the following night." (PMID 31611821, 2019). "In the pairwise meta-analysis, we observed that metformin had lower incidence of maternal hypoglycemia compared with insulin (RR, 0.28; 95% CI, 0.10 to 0.75; P = 0.05)." (PMID 31781670, 2019). "Previously, two studies have demonstrated that patients with CKD experienced severe hypoglycemia, which required ED visits or hospitalization, especially in patients who received insulin and sulfonylurea treatments." (PMID 30934740, 2019). "The availability of insulin pumps communicating with CGM sensors has stimulated the development of algorithms for the automatic suspension or attenuation of basal insulin delivery when hypoglycemia is either detected or predicted from CGM readings." (PMID 30922295, 2019). "Based on meta-analyses, degludec mediates equivalent reductions in HbA1c with a lower risk of hypoglycaemia compared with glargine U100 at a significantly lower total daily insulin dose in T1DM and T2DM with basal-only insulin." (PMID 31796048, 2019). "If hypoglycemia is occurring in this setting then management options include: carbohydrate consumption or reduction of basal insulin." (PMID 31258513, 2019). "Several animal studies have reported that experimental hypoglycemia induced by injections of excess insulin in rats resulted in Wallerian-type axonal degeneration." (PMID 31356602, 2019). "Furthermore, recent registration trials and postmarketing studies have suggested that newer long-acting insulin analogs may address some of the unmet needs of current basal insulin options in terms of risk of hypoglycemia, dosing time inflexibility, treatment adherence, and treatment satisfaction." (PMID 31976334, 2019). "The aetiology of hypoglycaemia in CP-DM is multifactorial and includes the use of insulin, impaired counterregulatory responses, glycogen storage deficits, malnutrition, and malabsorption as well as alcohol consumption." (PMID 31687406, 2019). "In conclusion, basal insulin attenuation algorithms are a promising technique for the mitigation of hypoglycemia in SAP therapy and represent the first step towards a fully closed-loop system." (PMID 30922295, 2019). "Risks of NICU admission and neonatal hypoglycemia were lower in the metformin group and reached a statistically significant level when compared with insulin (RR, 0.75; 95% CI, 0.64 to 0.87; P < 0.001; RR, 0.57; 95% CI, 0.49 to 0.66; P < 0.001; respectively)." (PMID 31781670, 2019). "Exercise performed when plasma insulin is close to basal levels (e.g., in the morning prior to breakfast) is less likely to result in hypoglycemia as circulating insulin levels are typically low." (PMID 31258513, 2019). "Our patient had multiple factors that triggered the episode of fulminant hepatic failure including the septic episode, hypoglycemia secondary to the intensive insulin therapy, and chronic diarrhea." (PMID 30922274, 2019). "We compared self‐reported hypoglycaemia (n = 160), HbA1c, insulin dose and microvascular complications (n = 140) in those with preserved and low C‐peptide." (PMID 30955221, 2019). "Use of anti-diabetic agents, especially sulfonylurea, glinide, and insulin, warrants close glucose level monitoring and dose adjustments to prevent hypoglycemia." (PMID 30934740, 2019). "Classical insulin autoimmune syndrome (IAS) is characterized by extremely high serum insulin concentrations, as well as spontaneous hypoglycemia." (PMID 31883520, 2019). "Of interest is the evidence that, among insulin-treated patients, the frequency of access to emergency department because of hypoglycemia was lower for patients with prescribed glucagon than that of other patients." (PMID 31349701, 2019). "Despite stopping her insulin, she continued to have hypoglycemia necessitating the administration of high concentrations of intravenous dextrose." (PMID 31156561, 2019).